U2 (U2 spliceosomal RNA )
Synonyms: LOC124904146
Gene: Small nuclear RNA gene on chromosome 17 (43,273,101 to 43,273,292, reverse strand). Ensembl gene ENSG00000278774.
Gene Ontology:
Molecular function: pre-mRNA branch point binding
Biological process: mRNA branch site recognition
Cellular component: U2 snRNP
Homologues: Orthologues: chimpanzee U2 (99% identical), macaque U2 (99% identical), dog U2 (99% identical), dog U2 (98% identical), pig U2 (47% identical), rat LOC120094029 (35% identical). Paralogues in human: U2 (99% identical), RNU2-2 (95% identical), U2 (95% identical), RNU2-3P (93% identical), RNU2-4P (93% identical), RNU2-17P (90% identical), RNU2-6P (89% identical), RNU2-48P (89% identical), RNU2-52P (89% identical), RNU2-59P (89% identical), RNU2-25P (87% identical), RNU2-26P (87% identical), and 68 more.